FBRSL1 (fibrosin like 1)
Synonyms: KIAA1545
Tractability: Antibody: the Human Protein Atlas places it where antibodies can reach. PROTAC: UniProt records ubiquitination sites on it; ubiquitination databases record sites on it.
Gene: Protein-coding gene on chromosome 12 (132,489,551 to 132,585,188, forward strand). Ensembl gene ENSG00000112787.
Subcellular location (Human Protein Atlas): Cytosol; Nucleoplasm; Plasma membrane
Gene Ontology:
Molecular function: RNA binding
Genetic constraint (gnomAD): Loss-of-function variants: 50 observed, 71.69 expected, observed/expected ratio (o/e) 0.7, 90% interval 0.56 to 0.88. The synonymous counts are far from expectation, so gnomAD's model fits this gene poorly and the ratio says little. Missense variants: 1,484 observed, 1,105.8 expected, observed/expected ratio (o/e) 1.34, 90% interval 1.28 to 1.4. Synonymous variants: 703 observed, 521.15 expected, observed/expected ratio (o/e) 1.35, 90% interval 1.27 to 1.44.
Homologues: Orthologues: macaque FBRSL1 (90% identical), chimpanzee FBRSL1 (90% identical), mouse Fbrsl1 (71% identical), dog FBRSL1 (66% identical), tropical clawed frog fbrsl1 (54% identical), guinea pig FBRSL1 (50% identical), rat Fbrsl1 (39% identical), zebrafish fbrsl1 (33% identical). Paralogues in human: AUTS2 (40% identical), FBRS (29% identical).
Diseases named in the same sentence as FBRSL1 in open-access papers:
FBRSL1 is named in the same sentence as 17 diseases in open-access papers, as found by Europe PMC text mining. Sharing a sentence is not in itself a finding about the gene and the disease. The quoted sentences say what the papers report.
AUTS2 syndrome (5 papers, 2020 to 2025). "The first description of causative mutations in the FBRSL1 paralogue AUTS2 (NG_034133.1) gene (AUTS2 syndrome, OMIM 615834) was reported in 2013." (PMID 39062605, 2024). "The clinical phenotype of this novel malformation syndrome caused by FBRSL1 variants partially overlaps with the severe form of AUTS2 syndrome." (PMID 39062605, 2024). "Comparison of clinical features seen in patients with FBRSL1 mutation and patients with AUTS2 syndrome." (PMID 34805182, 2021). "Some patients with AUTS2 syndrome also show additional symptoms like heart defects and contractures overlapping with the phenotype presented by patients with FBRSL1 mutations." (PMID 34805182, 2021). "As the patients carrying FBRSL1 variants showed features associated with AUTS2 syndrome, we also used the ASSS to compare the phenotype of the three patients with a variant in FBRSL1 to patients with AUTS2 syndrome." (PMID 34805182, 2021). "Our patients presented with features of the AUTS2 syndrome and additional symptoms, suggesting that mutations in FBRSL1 produce a more complex phenotype than mutations in the paralogue AUTS2." (PMID 32424618, 2020). "Interestingly, the phenotype associated with the AUTS2 syndrome and the FBRSL1-associated syndrome overlaps to a considerable extent." (PMID 40658195, 2025). "Interestingly, the clinical phenotype of the newly described malformation syndrome caused by FBRSL1 variants partially overlaps with the severe form of AUTS2 syndrome." (PMID 34805182, 2021). "The function of FBRSL1 is largely unknown, but pathogenic variants in the FBRSL1 paralog Autism Susceptibility Candidate 2 (AUTS2) are causative for an intellectual disability syndrome with microcephaly (AUTS2 syndrome)." (PMID 34805182, 2021). "Interestingly, mutations in the FBRSL1 paralogue AUTS2 lead to an intellectual disability syndrome (AUTS2 syndrome)." (PMID 32424618, 2020). "In contrast to AUTS2 syndrome, where the C terminus containing the AUTS2 domain is mostly relevant, the situation is different for the FBRSL1-associated syndrome." (PMID 38501224, 2024). "A remarkable clinical overlap between the FBRSL1 syndromic phenotype and the severe form of AUTS2 syndrome was observed." (PMID 34805182, 2021). "AUTS2 syndrome is caused by pathogenic variants in AUTS2, a paralogous gene of FBRSL1." (PMID 40658195, 2025).
microcephaly (4 papers, 2020 to 2025). A congenital or acquired developmental disorder in which the circumference of the head is smaller than normal for the person's age and sex. "Reminiscent of the malformations observed in patients affected by the FBRSL1-associated syndrome, patients with craniofacial spliceosomopathies show microcephaly, intellectual disability, heart defects and craniofacial malformations." (PMID 41283296, 2025). "As the patients carrying a FBRSL1 mutation developed microcephaly, we analyzed the development of the brain by Ncam immunostaining in Xenopus laevis embryos." (PMID 32424618, 2020). "We report truncating de novo variants in specific exons of FBRSL1 in three unrelated children with an overlapping syndromic phenotype with respiratory insufficiency, postnatal growth restriction, microcephaly, global developmental delay and other malformations." (PMID 32424618, 2020).
autism (3 papers, 2020 to 2025). Persistent deficits in social interaction and communication and interaction as well as a markedly restricted repertoire of activity and interest as well as repetitive patterns of behavior. "Interestingly, for each of the genes CIB2, FBRSL1, PACS2, KDM4B, and MYT1L, we found 2 individuals with autism with de novo variants in DAEs interacting with these genes." (PMID 34663447, 2021).
intellectual disability syndrome (3 papers, 2020 to 2025). "FBRSL1-associated syndrome is a rare congenital malformation and intellectual disability syndrome caused by heterozygous truncating variants in Fibrosin-Like 1 (FBRSL1)." (PMID 40658195, 2025). "Patients carrying certain variants of a gene that codes the fibrosin-like 1 (FBRSL1) protein suffer from a rare malformation and intellectual disability syndrome, characterised by a wide spectrum of clinical symptoms including CHD." (PMID 38501224, 2024).
developmental delay (2 papers, 2020 to 2025). "The FBRSL1-associated syndrome is a rare monogenic DD characterized by global developmental delay, multiple dysmorphic features, and congenital organ malformations." (PMID 40658195, 2025).
asthma (1 paper, 2022). "The associations of PRKRA and FBRSL1 CNVs with asthma were also abolished by conditioning on certain HLA variants." (PMID 35597955, 2022). "The final two asthma-associated CNVs are partial gene duplications on chromosome 2 (affecting exons 4–8 of the PRKRA gene and the 3’ end of the CHROMR long non-coding RNA gene) and chromosome 12 (affecting exon 2 of the FBRSL1 gene)." (PMID 35597955, 2022).
COVID-19 (1 paper, 2022). A disease caused by infection with severe acute respiratory syndrome coronavirus 2. "Other genes, such as ELF5 and FBRSL1 have no previously reported lung trait associations, and therefore, will need further mechanistic characterization to understand their role in severe COVID-19." (PMID 35360730, 2022).
mastitis (1 paper, 2023). Inflammation of breast tissue during lactation or postpartum due to an obstructed duct or infection. "The fourth locus that correlates with mastitis among LZG animals comprises FBRSL1, which encodes a protein with RNA binding activity belonging to the polycomb complex." (PMID 37685039, 2023).
malformation syndrome (3 papers, 2020 to 2024). "We have recently described a congenital malformation syndrome, caused by heterozygous truncating variants in FBRSL1." (PMID 38501224, 2024). "Recently, we identified truncating variants in the FBRSL1 gene in three unrelated children with an unknown malformation syndrome." (PMID 34805182, 2021). "Therefore, it is likely that further uncharacterized PRC-associated proteins, like FBRSL1, are also associated with a malformation syndrome." (PMID 32424618, 2020).
autosomal recessive disease (1 paper, 2023). Autosomal recessive form of disease. "With our study, we provided Moderate or Strong level of evidence for GDR for 11 genes that were not listed in OMIM as having phenotype entity: FBRSL1, AGR2, ACBD6, C1orf127, PAN2, VPS50, KCTD3, NOTCH3 (for autosomal recessive disease), FAT1, NRAP, and SCLT1." (PMID 39669245, 2023).
cardiovascular diseases (1 paper, 2022). "In cardiovascular diseases, the genes FBRSL1, IL10RB, ACE2 and ABO were those that were outstanding." (PMID 36430729, 2022).
neurodevelopmental disorder (1 paper, 2025). A behavioral and cognitive disorder with onset during the developmental period that involves impaired or aberrant development of intellectual, motor, or social functions. "We demonstrate that FBRSL1 associates with the transcription factor Yin Yang 1 (YY1) and binds upstream of Bromodomain And PHD Finger containing 1 (BRPF1) and Lysine Acetyltransferase 6 A (KAT6A), two epigenetic regulators involved in embryonic development and linked to neurodevelopmental disorders." (PMID 40658195, 2025).
FBRSL1 also shares sentences with these, for which no sentence is quoted: epilepsy (1 paper); fibrosis (1); Intellectual disability (1); Respiratory insufficiency (1); Sepsis (1).